SERPINH1 (serpin family H member 1)
Diseases named in the same sentence as SERPINH1 in open-access papers (continued):
Sharing a sentence is not in itself a finding about the gene and the disease.
osteosarcoma (9 papers, 2020 to 2025). A usually aggressive malignant bone-forming mesenchymal neoplasm, predominantly affecting adolescents and young adults. "Further research is still needed to determine the precise processes underlying the osteosarcoma pathogenesis mediated by SERPINH1." (PMID 37091161, 2023). "In an osteosarcoma study, Serpinh1 was demonstrated to exhibit positive correlations with multiple programmed cell death pathways, including pyroptosis, apoptosis, and ferroptosis." (PMID 41007677, 2025). "The IHC results further demonstrated that osteosarcoma tumor tissues had much greater levels of SERPINH1 expression than did normal tissues." (PMID 37091161, 2023). "As SERPINH1 has been widely studied in pan-cancer except for osteosarcoma, the prognostic value of SERPINH1 in osteosarcoma was reasonably expected." (PMID 37091161, 2023). "SERPINH1 and the SERPINH1-related score predict ferroptosis/pyroptosis/apoptosis/necroptosis in osteosarcoma." (PMID 37091161, 2023). "We, therefore, paid special attention to SERPINH1 and performed a comprehensive analysis on its role in osteosarcoma." (PMID 37091161, 2023). "As expected, the SERPINH1-related score efficiently stratified the survival outcomes of osteosarcoma patients and served as an independent prognostic factor." (PMID 37091161, 2023). "In this study, osteosarcoma patients with high SERPINH1-related scores had lower immune infiltrating cells, including as T cells, B cells, NK cells, macrophages, mast cells, Type 1 T helper cells, and Type 2 T helper cells." (PMID 37091161, 2023). "We focused specifically on SERPINH1, which has drawn more attention from the scientific community since it is more likely to contribute to the development of osteosarcoma as a malignancy." (PMID 37091161, 2023). "The biological function, immunological characteristics, and treatment response (immunotherapy and chemotherapy responses) of patients with osteosarcoma were successfully predicted using a model related to SERPINH1." (PMID 37091161, 2023). "Most importantly, patients with osteosarcoma who had low SERPINH1-related scores had a higher likelihood of responding to anti-PD-1 immunotherapy." (PMID 37091161, 2023). "It has been established that SERPINH1 is crucial in controlling how biological processes in osteosarcoma are carried out." (PMID 37091161, 2023). "In patients with osteosarcoma, SERPINH1 and SERPINA7 were found to be two independent prognostic indicators by univariate Cox regression analysis on the serpin superfamily." (PMID 37091161, 2023). "The physical function, immunological characteristics, and medication response of patients with osteosarcoma were successfully predicted using a SERPINH1-related model." (PMID 37091161, 2023). "In conclusion, the biological role of SERPINH1 in osteosarcoma was investigated using in vitro confirmation." (PMID 37091161, 2023). "Patients with osteosarcoma who had high SERPINH1-related scores had significantly lower drug sensitivity to AMG-319 2045, AZD3759 1915, AZD8186 1918, Cisplatin 1005, CZC24832 1615, Dactinomycin 1811, Dactolisib 1057, Entospletinib 1630, Foretinib 2040, GSK343." (PMID 37091161, 2023). "The SERPINH1-related score was an effective method for identifying osteosarcoma patients who would respond to immunotherapy and chemotherapy, as well as for predicting the survival outcomes of such patients." (PMID 37091161, 2023). "Patients with osteosarcoma were divided into two groups according to the expression level of SERPINH1, and it was shown that the two groups had dramatically different survival rates." (PMID 37091161, 2023). "The likelihood of patients with osteosarcoma responding to anti-PD-1 immunotherapy was significantly higher in those with low SERPINH1-related scores." (PMID 37091161, 2023).
osteosarcoma (continued). "Serpinh1 is a protein playing a role in collagen biosynthesis, that enhances the malignancy in osteosarcoma, but its role in melanoma is not well understood, while osteopontin and Mmp3 are involved in cell adhesion, migration and in vivo tumor growth of melanoma." (PMID 39457009, 2024). "Additionally, immune cells are interacted with through checkpoint, cytokine, and growth factor pathways in osteosarcomas with high SERPINH1 levels." (PMID 37091161, 2023). "In osteosarcoma patients with high SERPINH1-related scores, an immune-cold microenvironment that promotes tumor development may exist." (PMID 37091161, 2023). "According to the CCK-8, EdU, and Transwell assays as well as the IHC assay, SERPINH1 may promote osteosarcoma proliferation and migration." (PMID 37091161, 2023). "Additionally, 23 chemotherapeutic agents had significantly decreased drug sensitivity in osteosarcoma patients with high SERPINH1-related scores." (PMID 37091161, 2023). "The SERPINH1-related score was accurate at identifying osteosarcoma patients who could respond to immunotherapy." (PMID 37091161, 2023). "SERPINH1-related score was used to classify osteosarcoma patients." (PMID 37091161, 2023). "It was discovered that SERPINH1 is a significant biological marker in osteosarcoma." (PMID 37091161, 2023). "It was investigated how SERPINH1 functions biologically in osteosarcoma." (PMID 37091161, 2023). "Notably, SERPINH1 and the SERPINH1-related score predict ferroptosis/pyroptosis/apoptosis/necroptosis in osteosarcoma." (PMID 37091161, 2023). "Therefore, the SERPINH1-related score was accurate in identifying osteosarcoma patients who could respond to chemotherapy." (PMID 37091161, 2023).
fibrosis (8 papers, 2013 to 2025). the formation of excess fibrous connective tissue in an organ or tissue in a reparative or reactive process. "This reflected possible similar pathogenesis between keloids and vocal fold mucosal fibrosis with the participation of SERPINH1." (PMID 33860039, 2021). "Furthermore, these findings contrast not only published in vitro studies but also in vivo studies; antifibrotic effects of Serpinh1-targeting siRNA have been previously observed in various fibrosis models, such as pulmonary, hepatic, renal, peritoneal, and dermal fibrosis." (PMID 33659262, 2021).
keloid (8 papers, 2010 to 2025). An irregularly shaped, elevated mark on the skin caused by deposits of excessive amounts of collagen during wound healing. "The results of the FOXP1-Cut&Tag experiment in keloid fibroblasts revealed that FOXP1 is associated with the SEs of SERPINH1, MMP14, COL5A1, COL16A1, and SPARC, all of which exhibited significant signal enrichment in their SE regions." (PMID 40702440, 2025). "SERPINH1 has been suggested to stimulate excessive collagen deposition in keloids." (PMID 32085797, 2020). "A statistically significant (P < .05) differential expression and a fold change of more than 2 were determined between keloid margin and internal control biopsy samples for 10 genes, including ACAN, ASPN, C5orf13, HIF1A, IGFBP7, INHBA, LGALS1, PTN, SERPINH1, and TNFAIP6." (PMID 20418938, 2010).
cervical squamous cell carcinoma (7 papers, 2013 to 2025). A squamous cell carcinoma arising from the cervical epithelium. "High SERPINH1 protein levels have also been reported in esophageal squamous cell carcinoma, cervical squamous cell carcinoma, and ulcerative colitis-associated carcinomas." (PMID 32091407, 2020). "This study systematically reveals the key role of SERPINH1 (Serpin Family H Member 1) as a hub regulator of malignant progression in cervical squamous cell carcinoma and endocervical adenocarcinoma (CESC)." (PMID 40705756, 2025). "Suppression of SERPINH1 expression with short interfering RNAs has been shown significantly inhibit cell proliferation, migration, and invasion in cervical squamous cell carcinoma." (PMID 35058967, 2021).
clear cell renal cell carcinoma (7 papers, 2018 to 2025). "For instance, circ-TNPO3 bound to IGF2BP2, resulting in destabilization of SERPINH1 mRNA in clear cell renal cell carcinoma." (PMID 40883266, 2025). "A similar functional mechanism was founded in clear cell renal cell carcinoma, suggesting that circTNPO3 might downregulate the stability of SERPINH1 mRNA, a type of oncogene, by competitively binding to IGF2BP2." (PMID 40822457, 2025). "Moreover, a high level of SERPINH1 is reported in clear cell renal cell carcinoma." (PMID 36415513, 2022).
Obesity (7 papers, 2021 to 2025). Accumulation of substantial excess body fat. "Could blocking the endothelial production of SERPINH1 protect against the development of cardiovascular diseases associated with aging and obesity?" (PMID 33847560, 2021). "The levels of expression of one gene in this cluster (a gene called Serpinh1) were increased by aging and obesity, and decreased by exercise in both young and old mice." (PMID 33847560, 2021). "Four genes were identified to be significantly affected by aging, obesity, and exercise (Serpinh1, Vwa1, Mest, and Fhl3)." (PMID 33661096, 2021). "We identified collagen chaperone Serpinh1 (also called as Hsp47) to be significantly increased by aging and obesity and repressed by exercise training." (PMID 33661096, 2021). "Analysis of potential disease-promoting genes identified Serpinh1 to be induced by aging and obesity, while its expression was significantly repressed by exercise, also in old mice." (PMID 33661096, 2021). "Serpinh1 expression is increased by aging and obesity and repressed by exercise training." (PMID 33661096, 2021). "Two genes, Serpinh1 and Vwa1, were found to be significantly increased by both aging and obesity and decreased by exercise, suggesting that they could act as common mediators of EC dysfunction." (PMID 33661096, 2021). "It was found that the mRNA expression levels of STAT3, CORO1C, SERPINH1, MVP and ITGB5 were significantly increased in the obesity compared with the control group." (PMID 34248836, 2021).
cervical cancer (6 papers, 2017 to 2025). A primary or metastatic malignant neoplasm involving the cervix. "Despite these advances, the specific functions and regulatory mechanisms of SERPINH1 in cervical cancer development and progression remain poorly understood." (PMID 40705756, 2025). "Based on previous analyses suggesting the tumor-promoting role of SERPINH1, we evaluated its impact on the malignant phenotypes of cervical cancer cells through functional experiments." (PMID 40705756, 2025). "The knockdown and overexpression studies of SERPINH1 confirmed that SERPINH1 regulates the malignant phenotypes of cervical cancer, promoting its proliferation, migration, and invasion." (PMID 40705756, 2025). "Initially, we selected two cervical cancer cell lines, Siha and C33A, and established stable overexpression models of SERPINH1 via lentiviral transduction." (PMID 40705756, 2025). "To investigate the functional role of SERPINH1 in cervical cancer, we performed a genome-wide correlation analysis using the TCGA-CESC dataset." (PMID 40705756, 2025). "In vitro experiments validated these findings, demonstrating that SERPINH1 overexpression markedly enhanced the proliferation, invasion, and metastasis of cervical cancer cells, whereas its knockdown substantially inhibited these processes." (PMID 40705756, 2025). "Overall, our findings underscore the multiple functions of SERPINH1 as a hub for cervical cancer metastasis regulation, suggesting its potential as a promising biomarker for tailoring strategies in metastasis patients of CESC." (PMID 40705756, 2025). "Additionally, SERPINH1 expression levels were significantly positively correlated with the histological grade of cervical cancer." (PMID 40705756, 2025). "Through differential expression analysis of cervical cancer GEO datasets GSE9750 and GSE63514, we identified a significant upregulation of SERPINH1 expression in tumor tissues compared to normal controls (p < 0.001)." (PMID 40705756, 2025). "Taken together, these findings suggest that SERPINH1 is likely involved in the malignant progression of cervical cancer and influences patient prognosis, rather than playing a role in tumor initiation." (PMID 40705756, 2025).
myocardial infarction (5 papers, 2019 to 2025). Gross necrosis of the myocardium, as a result of interruption of the blood supply to the area, as in coronary thrombosis. "The SERPINH1 was also associated with cardiac fibrosis following myocardial infarction." (PMID 35118144, 2021).
rheumatoid arthritis (5 papers, 2008 to 2024). A chronic, systemic autoimmune disorder characterized by inflammation in the synovial membranes and articular surfaces. "Human HSP47/SERPINH1 is associated several human diseases like rheumatoid arthritis, where autoantibodies to HSP47 protein have been found in rheumatoid arthritis patients." (PMID 28871169, 2017).
colon cancer (4 papers, 2019 to 2022). "Recent studies showed that in mouse models of colonic inflammation, SERPINH1 is expressed in infiltrating immune cells and plays a role in extracellular matrix remodeling that promotes colon cancer progression." (PMID 35323693, 2022). "In this regard, it has been recently demonstrated that in colon cancer, stromal HSF1 drives the transcription of genes encoding matrix proteins (FN1, LAMA1), matrix enzymes (MMP7, MMP9), and matrix chaperones (SERPINH1/Hsp47), inducing ECM remodeling and leading to cancer progression." (PMID 34198675, 2021).
COVID-19 (4 papers, 2021 to 2025). A disease caused by infection with severe acute respiratory syndrome coronavirus 2. "Overlapping genes for TSA and COVID-19 were SERPINH1, LPAR1, and TCEA2, and overlapping genes for TSA and MDD were NOL3, LPAR1, and HSPA6." (PMID 40918512, 2025).
hepatocellular carcinoma (4 papers, 2019 to 2025). A malignant tumor that arises from hepatocytes. "CAFs promote hepatocellular carcinoma malignancy by SERPINH1 secretion and regulating SENP3-mediated SP1/SQLE pathway." (PMID 40959099, 2025).
lung adenocarcinoma (4 papers, 2019 to 2024). A carcinoma that arises from the lung and is characterized by the presence of malignant glandular epithelial cells. "SERPINH1 has been reported to be highly expressed in lung adenocarcinoma tissue, and the SERPINH1 low-expression group had a higher survival rate than the high-expression group." (PMID 37760828, 2023).
adenoma (3 papers, 2009 to 2022). A neoplasm arising from the epithelium. "We then used this approach to achieve knockdown of RRP12 and SERPINH1 in adenoma organoids established from fresh surgical specimens; the effectiveness of the knockdown process was confirmed by ddPCR." (PMID 34194496, 2021). "Research showed that SERPINH1 could be a serum marker in diagnosis and prognosis assessment of GC and potentially be the noninvasive biomarker reflecting the adenoma and carcinoma, especially CRC." (PMID 36105106, 2022). "Furthermore, RRP12 and SERPINH1 knockdown impeded the viability and proliferation of adenoma organoids." (PMID 34194496, 2021). "Therefore, we explored the influence of RRP12 or SERPINH1 on the viability of adenoma cells at the organoid level." (PMID 34194496, 2021). "Hence, SERPINH1 could potentially be the noninvasive biomarker reflecting the adenoma and carcinoma progression." (PMID 34194496, 2021).
cardiac hypertrophy (3 papers, 2018 to 2021). "Additionally, cardiac fibrosis after pressure overload injury was also associated with the increased levels of SERPINH1, collagen I, III, and V and, moreover, myofibroblast-specific deletion of SERPINH1 reduced fibrosis and cardiac hypertrophy." (PMID 35118144, 2021).
endothelial dysfunction (3 papers, 2018 to 2021). In vascular diseases, endothelial dysfunction is a systemic pathological state of the endothelium (the inner lining of blood vessels) and can be broadly defined as an imbalance between vasodilating and vasoconstricting substances produced by (or acting on) the endothelium. "Recent studies showed that SERPINH1 increased in mouse cardiac endothelial cells and this increase was associated with endothelial dysfunction and impaired vascular remodeling." (PMID 35118144, 2021). "SERPINH1 (rs590121 lead SNP) is predicted to increase risk of hemorrhage; DDX59-CAMSAP2 (rs1867624) may be involved abnormal vascular development; PECAM1 (rs1867624) may regulate vascular inflammation and endothelial dysfunction; and LMOD1 (rs2820315) is implicated in SMC differentiation." (PMID 30444878, 2018).
epidermoid carcinoma (3 papers, 2014 to 2023). "SERPINH1 (Serpin Family H Member 1), also known as HSP47, is an important stress-related protein on the endoplasmic reticulum, with higher expression in squamous carcinoma tissues than in normal human bronchial epithelial cells." (PMID 37328788, 2023).
stomach adenocarcinoma (3 papers, 2021 to 2024). "SERPINH1 is abnormally expressed and has been suggested as a potential prognostic biomarker in stomach adenocarcinoma." (PMID 39305996, 2024).
stomach cancer (3 papers, 2010 to 2025). "One gene, serpin peptidase inhibitor, clade H, member 1 (SERPINH1), the gene encoding HSP47, was upregulated in gastric tumor tissues." (PMID 38907287, 2024).
Alzheimer’s dementia (2 papers, 2009 to 2025). "In the cortex, SERPINH1+ astrocytes were also more abundant in the STG in individuals with a clinical diagnosis of Alzheimer’s dementia." (PMID 40584839, 2025).
atrial fibrillation (2 papers, 2021). A disorder characterized by an electrocardiographic finding of a supraventricular arrhythmia characterized by the replacement of consistent P waves by rapid oscillations or fibrillatory waves that vary in size, shape and timing and are accompanied by an irregular ventricular response. "For example, it has been reported that the protein encoded by SERPINH1 – heat shock protein 47 – co-localizes with endothelial-to-mesenchymal markers in endothelial cells from patients with atrial fibrillation." (PMID 33847560, 2021).
cardiac ischemia (2 papers, 2024 to 2025). "In another study, the opioid peptide SLP was shown to suppress the expression of Serpinh1 following myocardial ischemia/reperfusion injury (MI/RI) in mice." (PMID 41007677, 2025).
invasive carcinoma (2 papers, 2009 to 2020). A carcinoma that is not confined to the epithelium, and has spread to the surrounding stroma. "However, macrophages expressing either MORC4 or SERPINH1 together with CD206 were positively correlated with patient survival, although their numbers did not significantly change in invasive carcinoma compared with DCIS or normal breast tissue." (PMID 33377644, 2020).
lymphoma (2 papers, 2022). A malignant (clonal) proliferation of B- lymphocytes or T- lymphocytes which involves the lymph nodes, bone marrow and/or extranodal sites. "The results revealed that SERPINH1 mRNA level was significantly highly expressed in bladder, brain and CNS, breast, colorectal, esophageal, gastric, head and neck, leukemia, lung, lymphoma, ovarian, pancreatic, and other cancers in comparison to corresponding normal tissues." (PMID 36105106, 2022).
metastatic disease (2 papers, 2010 to 2020). "SERPINH1 (HSP47) was also associated with metastatic disease and had been shown earlier to be a marker for metastatic tumour cells." (PMID 21092330, 2010).
nasopharyngeal carcinoma (2 papers, 2022 to 2023). A carcinoma arising from the nasopharyngeal epithelium. "Splicing factor-derived circular RNA circCAMSAP1 was reported to accelerate the tumorigenic process of nasopharyngeal carcinoma via a SERPINH1/c-Myc positive feedback loop." (PMID 37091161, 2023).
ovarian carcinoma (2 papers, 2021 to 2022). A malignant neoplasm originating from the surface ovarian epithelium. "Furthermore, the expression of SERPINH1 was high in patients in gene cluster C. Previous studies have shown that CNDP2 is pro-oncogene, involved in cell proliferation and metastasis in ovarian cancer via the PI3K/AKT pathway." (PMID 36700224, 2022).